CRP (C-reactive protein)
Diseases named in the same sentence as CRP in open-access papers (continued):
Sharing a sentence is not in itself a finding about the gene and the disease.
bacterial infection (continued). "Employing CRP RDTs in the diagnosis of febrile children in rural, resource-limited settings may aid in identifying those at high risk for bacterial infection requiring antibiotics, while also reducing overuse of antibiotics in low-risk children and expanding equitable access to diagnostic tools." (PMID 38241274, 2024). "Additionally, CRP, a diagnostic marker reflecting bacterial infection, also showed an increase." (PMID 38830934, 2024). "Some studies have suggested that PCT may offer greater diagnostic accuracy than CRP due to its higher specificity for bacterial infections, while others have highlighted the value of CRP as a marker of inflammation that can complement PCT in the diagnostic process." (PMID 39469363, 2024). "However, the diagnostic value of CRP alone for bacterial infections is considered only moderate." (PMID 38109177, 2023). "CRP was reported to be notably elevated in bacterial infections; acidic environments (systemic inflammation) may have triggered pathogenic and more virulent bacterial transformations, that can possibly lead to elevated CRP." (PMID 37873776, 2023). "Furthermore, it has been demonstrated that immune disfunction such as the presence of anti-IL-6 autoantibodies may be associated with normal levels of CRP even in presence of a bacterial infection." (PMID 36673130, 2023). "Plasma levels of DLL1 following LTX may be useful to support an earlier detection of bacterial infections in combination with C-reactive protein (CRP) and procalcitonin (PCT), or they may lead to risk stratification of patients as a single marker for post-operative complications." (PMID 33142943, 2020). "Similarly, a recent cluster-randomized trial in pediatric primary care in Belgium assessing the use of CRP as a screening tool to rule out serious bacterial infection concluded that only children at higher risk for serious bacterial infection after clinical assessment should be tested using CRP." (PMID 29059253, 2017). "Moreover, the GPs underlined the possibility of an unspecified bacterial infection, spread in the body, which might present itself by the patient feeling sick, a bacterial smell or raised CRP." (PMID 27188438, 2016). "Regarding to the use of CRP as a diagnostic biomarker, when considered in asingle dosage, its sensitivity and specificity are limited for differentiatingbetween severe bacterial infection and benign or non-bacterial infection, forexample, in cases of pediatric emergency." (PMID 28099644, 2016). "However, this association may not be of a magnitude that makes it clinically important for CRP as a diagnostic tool in bacterial infections associated with a positive blood culture." (PMID 18706087, 2008). "Following treatment for multidrug-resistant bacterial infection and reamputation of the stumps, the patient’s CRP returned to normal ranges (the CRP was 12 mg/L on December 2, 2024)." (PMID 41560094, 2026). "After treatment for multidrug-resistant bacterial infection, the CRP decreased to 20 mg/L and remained stable between 30 mg/L and 20 mg/L after amputation." (PMID 41560094, 2026). "As an acute-phase protein, CRP rises in the body during infections and stress, especially in bacterial infections." (PMID 41313026, 2026). "On November 16, 2024, the patient was readmitted due to a recurrence of multidrug-resistant bacterial infection, with a CRP level of 98.24 mg/L." (PMID 41560094, 2026). "Apart from being a systemic inflammation marker in MP infections, increased CRP should also raise concern about the potential role of concurrent bacterial infections in MRMP-induced pulmonary consolidation." (PMID 41059988, 2025). "For example, both viral and bacterial infections lead to an elevation of CRP; thus in some patients making such differentiation is difficult by using these protein biomarkers." (PMID 40581066, 2025). "PCT has therefore been favored over C-reactive protein (CRP) as biomarker for the detection of bacterial infections." (PMID 40607352, 2025).
bacterial infection (continued). "In severe bacterial infection, the extremely high IL-6 levels overrun the so-formed IL-6 buffer, and CRP rises." (PMID 40632603, 2025). "Our model suggests that CRP can be a specific marker for distinguishing bacterial from non-bacterial infections, albeit as a standalone data point." (PMID 39177882, 2025). "CRP, an acute-phase protein, begins to increase at 4 to 6 h after the onset of bacterial infection, and peaks at about 24 to 48 h." (PMID 41291834, 2025). "This is in accordance with other studies suggesting that CRP is a useful marker to monitor animals with bacterial infections and to guide antimicrobial treatment." (PMID 40607352, 2025). "Because human CRP also possesses the broad capsule-binding activities, our findings provide a biological reason for the massive rise of plasma CRP during bacterial infections." (PMID 41214213, 2025). "We aimed to assess the diagnostic value of procalcitonin (PCT), white blood cell count (WBC), and C-reactive protein (CRP) levels for detecting bacterial infection and SIRS within the first week after LT." (PMID 41007066, 2025). "On admission, the patient was administered cefotaxime due to elevated C-reactive protein (CRP) levels suggestive of bacterial infection and became afebrile." (PMID 40842793, 2025). "In this case, at the time when both blood and ascitic fluid were collected for mNGS testing, concurrent blood tests showed WBC 2.6 × 109/L, N% 76%, Hb 111 g/L, and CRP 230 mg/L, consistent with secondary bacterial infection." (PMID 41321463, 2025). "C-reactive protein (CRP) is another widely studied biomarker that can aid in the early identification of bacterial infections." (PMID 40693097, 2025). "Given that acute-phase proteins typically increase during early bacterial infections, we measured CRP and SAA1 levels in BALF by ELISA." (PMID 40572197, 2025). "Although PCT levels are typically very low (< 0.1 ng/mL) in healthy individuals, they rise in response to bacterial infections, making PCT a more specific inflammatory marker of bacterial disease compared to CRP." (PMID 40067493, 2025). "CRP, PCT, and IL-6 are common diagnostic markers for bacterial infections, and when inflammation occurs, CRP, PCT, and IL-6 are released in large quantities and can be applied to evaluate treatment efficacy in patients." (PMID 40842537, 2025). "As a pro-inflammatory cytokine, IL-6 is released by immune cells (e.g., macrophages and T cells) in response to bacterial infection to initiate C-reactive protein production, making it a sensitive marker to monitor inflammation." (PMID 40867936, 2025). "There was also an ambition to distinguish low-severity from high-severity infections by using CRP to allow safe withholding of antibiotics from patients with self-limiting mild bacterial infections." (PMID 40887118, 2025). "Blood tests are largely used in the ED since they can help distinguish between viral and bacterial infection, and CRP performs better in predicting severe bacterial infection in young children than WBC count." (PMID 40506878, 2025). "Traditionally used host biomarkers, such as CRP and procalcitonin, often fail to discriminate between viral and bacterial infections in children." (PMID 40150663, 2025). "Otherwise, the patient had elevated white blood cell counts and CRP levels upon admission, and Klebsiella pneumoniae was detected in the bronchoalveolar lavage fluid, indicating a secondary bacterial infection in the context of lipoid pneumonia." (PMID 40604803, 2025). "CRP is an acute-phase response protein commonly used for the clinical evaluationand diagnosis of bacterial infection." (PMID 40026526, 2025). "CRP has demonstrated good sensitivity for bacterial infections at fever onset, though its specificity remains modest." (PMID 40647525, 2025). "A previous study investigating CRP values in HCC patients in context of bacterial infection, showed lower increase of CRP in contrast to patients with normal liver function." (PMID 41142780, 2025).
bacterial infection (continued). "Elevated leucocyte counts (15.16 g/L) and procalcitonin (0.52 μg/L) suggested possible bacterial infection, and despite low C-reactive protein levels (CRP, 0.8 mg/L), oral amoxicillin was started after obtaining blood cultures." (PMID 41164741, 2025). "The findings indicated that CRP had an AUC of 0.855 (95% CI, 0.771–0.917) in distinguishing bacterial infection, with an optimal cut-off value of 71.53 mg/L." (PMID 39946377, 2025). "Clinical trials demonstrate that calprotectin is at least as effective as C-reactive protein, procalcitonin, and white blood cell counts in predicting bacterial infections." (PMID 40650251, 2025). "Research has demonstrated that PCT levels rise more rapidly and are more sensitive in detecting bacterial infections compared to other biomarkers, such as CRP." (PMID 40150637, 2025). "The authors concluded that PCT was a more sensitive marker for bacterial infection in febrile neutropenic children and recommended its routine use, despite low specificity, while CRP’s low sensitivity renders it suboptimal for early detection." (PMID 40647525, 2025). "Even more so, the more pronounced increase in IL-6 found in bacterial infection will override the ‘buffer capacity’ of sIL-6 receptors and sgp130, and high levels of CRP will be produced." (PMID 40632603, 2025). "The analysis revealed that blood cortisol (OR = 1.007, 95% CI: 1.002–1.012, p = 0.003) and CRP (OR = 1.014, 95% CI: 1.002–1.026, p = 0.017) were two independent predictors of bacterial infection in DKA." (PMID 39946377, 2025). "The area under the receiver operating characteristic curve (AUC) for CRP in identifying bacterial infection was 0.855 (95% CI, 0.771–0.917), with a sensitivity of 76.1% and a specificity of 83.6%." (PMID 39946377, 2025). "First, blood tests showed no significant inflammatory markers (white blood cell count (WBC: 6,000/μL, C-reactive protein (CRP): 0.21 mg/dL) despite acute symptoms, which is atypical for bacterial infection." (PMID 40861727, 2025). "There was a significant difference in CRP levels between bacterial and non-bacterial infection classifications (p = 0·008)." (PMID 39177882, 2025). "Elevated C-reactive protein (CRP) levels result from bacterial infection, inflammation, and tissue necrosis." (PMID 40959356, 2025). "Several studies have identified CRP as a useful marker of exacerbation severity and an indicator of bacterial infection." (PMID 40918901, 2025). "Associations with CRP, underlying diseases, severe acute respiratory syndrome coronavirus type 2 (SARS-CoV-2) and bacterial infections were analysed." (PMID 39948564, 2025). "For patients with suspected BSI, the levels of procalcitonin (PCT) and CPR (C-reactive protein) can be used to evaluate the degree of bacterial infection and prognosis." (PMID 40365071, 2025). "The low levels of CRP measured in majority of participants in all intervention subgroups support the notion that most cases were likely viral or self-limiting bacterial infections." (PMID 41433251, 2025). "Different works show that it can perform better than C-reactive protein (CRP) for bacterial infection among inpatients and can also improve clinical outcomes." (PMID 40150077, 2025). "Because human and mouse CRPs showed a similar pattern of binding interactions with many capsule types, we expect that CRP serves an important immune function against invasive bacterial infections." (PMID 41214213, 2025). "CRP is useful in monitoring disease progression and treatment response in conditions such as bacterial infections, rheumatoid arthritis, cancer, and acute pancreatitis." (PMID 40650251, 2025). "Further confusion arose around a positive CRP result indicating a possible bacterial infection due to the fact that in everyday Khmer language, there is no distinction between viruses, bacteria, or parasites." (PMID 40340660, 2025).
bacterial infection (continued). "Plasma C-reactive protein (CRP) is widely used as a biomarker for bacterial infection, but its biological function remains obscure." (PMID 41214213, 2025). "The AUC value of PCT for predicting bacterial infection was significantly better compared to CRP or N/L ratio (p=0.042)." (PMID 40917823, 2025). "Traditional biomarkers, such as WBCs, CRP, and procalcitonin, often fail to discriminate viral and bacterial infections in children." (PMID 40150663, 2025). "CRP, an inflammatory marker, is upregulated in response to a variety of inflammation stimuli, including bacterial infections." (PMID 40150663, 2025). "Their study demonstrated that while under normal physiological conditions serum content of CRP is low, it abnormally increase in cases of bacterial infection, reaching its peak within 36-50 hours." (PMID 39926661, 2025). "In this context, massive increase in plasma CRP in humans during severe bacterial infections appears to represent an important host defense response to clear invasive bacteria from the bloodstream in the liver." (PMID 41214213, 2025). "Our study has identified cortisol and CRP as valuable markers that can aid in the early detection of bacterial infections in DKA patients." (PMID 39946377, 2025). "According to the findings in our study, CRP was an effective predictor of early bacterial infection in DKA, with a cut-off value of 71.53 mg/L, a sensitivity of 76.1%, and a specificity of 83.6%." (PMID 39946377, 2025). "Although many physicians state that they lack exact CRP cut-off levels for prescribing, CRP is often considered a reliable numerical measure of bacterial infection." (PMID 39460385, 2025). "Initial blood tests revealed elevated white blood cells, neutrophils, and C-reactive protein (CRP) levels, indicating a bacterial infection." (PMID 39449950, 2024). "Currently, CRP level is a common indicator for the diagnosis of bacterial infections, efficacy evaluation, and disease assessment." (PMID 39411281, 2024). "There is often a significant overlap in CRP levels between viral and bacterial infections, which can make accurate diagnosis challenging." (PMID 39840216, 2024). "Patients with BSI presented with significantly lower CRP/Neopterin ratios (median 0.08) than patients with bacterial infection only (median 0.34; p < 0.001)." (PMID 38930481, 2024). "Because of relatively high CRP levels four patients received antibiotic treatment, assuming a bacterial infection, which was stopped after the viral pathogen diagnosis." (PMID 38592660, 2024). "As model biomarkers we chose three cytokines (interleukin-6, interleukin-8, tumor necrosis factor alpha), the bacterial infection marker C-reactive protein and the bacterial pathogen Streptococcus pneumoniae—all relevant factors in exacerbation episodes." (PMID 38834656, 2024). "While previous studies reported a strong discriminatory capability of CRP for serious bacterial infection, we found its poor discriminatory capability for mortality." (PMID 39015209, 2024). "Interleukin-8 and CRP serve as markers for bacterial infections, thereby establishing a close association with Shigella infection." (PMID 38495509, 2024). "High inflammatory markers, such as the neutrophil count and CRP levels, as well as the increase in CRP within 48 h after admission, were also correlated with bacterial infection." (PMID 39315820, 2024). "Univariate regression analysis was conducted to assess the relationship between the copy number of mtDNA in red blood cells and CRP concentration in 64 patients with bacterial infection." (PMID 40046178, 2024). "Commonly, a bacterial infection can be diagnosed, prognosed, and monitored using CRP and WBC, with CRP being more sensitive." (PMID 38911027, 2024).
bacterial infection (continued). "Serum CRP, a highly sensitive acute-phase inflammatory protein, can increase in concentration by up to 1000-fold in response to certain bacterial infections, driven by enhanced genetic expression stimulated by cytokines though various immune pathways." (PMID 39767771, 2024). "In contrast, we excluded patients with bacterial infection, and median CRP levels were low (i.e. 0.3 [IQR 0.1–0.7] mg × L-1)." (PMID 38074505, 2024). "As patients with evidence of bacterial infections were excluded from our study, median CRP levels were low." (PMID 38074505, 2024). "This latter assertion is also supported by data from a study showing that a CRP level > 40 mg/ml had a sensitivity of 74% for detecting bacterial infections in acutely febrile patients." (PMID 38523864, 2024). "The increase of OPG was tightly correlated to the respective increase in CRP levels only in the bacterial infection group (rho = 0.428, p = 0.0011)." (PMID 38509997, 2024). "For acute exacerbations of COPD, CRP values above 40 mg/mL suggest bacterial infections, with an uncertainty range of 20 to 40 mg/mL." (PMID 39407829, 2024). "Serum levels of PCT and CRP, two markers of bacterial infection, were significantly lower in cats in the C.j + IgY group." (PMID 38655089, 2024). "For initial differentiation between bacterial and other pathogens levels of infectious parameters such as c-reactive protein are commonly used as an indicator for bacterial infections when strongly elevated." (PMID 38592660, 2024). "The study revealed that NLR, with an optimal threshold of seven, showed significance in the presence of 82 bacterial infection cases, and its Area Under the ROC Curve (AUC) was 0.64, comparable to CRP and PCT in this clinical context." (PMID 39296886, 2024). "Typically, CRP concentrations are considerably higher in bacterial infections as compared to viral ones." (PMID 38611597, 2024). "In summary, our results on the AUCs for NLR, PLR, and CRP align with the conclusions of previous studies, confirming the variable performance of these markers in predicting bacterial infections." (PMID 39296886, 2024). "Through univariate regression analysis of CRP concentration and the copy number of mtDNA bound to red blood cells in 64 bacterial infection patients, we observed a positive correlation." (PMID 40046178, 2024). "In normal patients, serum CRP levels are low and often rise to a peak within a short period of time (1-2 days) in response to bacterial infection and inflammation." (PMID 38196482, 2024). "C-reactive protein (CRP), a major acute-phase protein, is involved in both innate and adaptive immunity against bacterial infection." (PMID 39206200, 2024). "Marked elevations of both calprotectin and CRP were observed, particularly in patients with bacterial infection." (PMID 38786153, 2024). "Although these values indicate a reasonable ability of these markers to differentiate bacterial infections from other pathologies, CRP showed the highest AUC of 0.82, highlighting its superior effectiveness in predicting bacterial infections." (PMID 39296886, 2024). "PCT and CRP, as commonly used clinical indicators for diagnosing bacterial infections, have certain limitations when used individually as compared to their combined use." (PMID 39724075, 2024). "Both PCT and CRP have been extensively studied for their use in the detection of bacterial infections." (PMID 39283042, 2024). "Among these markers, Procalcitonin (PCT) stands out due to its notable specificity for bacterial infections compared to other markers like C-reactive protein (CRP) or white blood cell count (WBC)." (PMID 39420348, 2024). "This is consistent with previous findings where it was observed that CRP is more sensitive than procalcitonin in differentiating local bacterial infections." (PMID 39185468, 2024).